IDO1 (indoleamine 2,3-dioxygenase 1)
Diseases named in the same sentence as IDO1 in open-access papers (continued):
Sharing a sentence is not in itself a finding about the gene and the disease.
cancer (continued). "Remarkably, 11C-l-1MTrp signal intensity in the MLNs was inversely related to the specific growth rates of treated tumors, suggesting that IDO1 expression in the MLNs can serve as a new biomarker of the cancer-immune set point." (PMID 34148865, 2021). "As epacadostat has been shown to be a more specific inhibitor of IDO1 and was tested in clinical trials for several cancer entities, we further analyzed its effects in the TCL1 mouse model." (PMID 33920868, 2021). "Herein, we describe an accurate high-pressure liquid chromatography coupled with a diode array detector (HPLC-DAD) method to serve for IDO1 activity determination in human cancer cells cultured in vitro." (PMID 33541164, 2021). "A study reported that IDO1 is with higher mRNA transcription and protein expression level than in normal cervix, and also in comparison to other cancers." (PMID 34778035, 2021). "We also discuss various strategies for cancer treatment via regulating IDO1-dependent dormancy and suggest the application of nanotechnology to deliver effective treatment." (PMID 34539663, 2021). "The IDO1 activity assay was based on measuring ʟ-Kyn formation rate generated by the enzyme present in the cytoplasmic fraction of the cancer cell lysate." (PMID 33541164, 2021). "A comprehensive analysis of the expression and biological function of IDO1 can help us to understand the therapeutic strategies of the inhibitors targeting IDO1 in malignant tumors." (PMID 35003126, 2021). "Recent clinical studies have aimed to identify appropriate methods to enable IDO1 regulation monitoring, as well as to determine the cancer-immune status and predict the therapeutic efficacy of IDO1-based combinatorial immunotherapies." (PMID 34148865, 2021). "In this review, we aim to provide a timely and updated summary on the structural biology and biological functions of IDO1 as well as cancer immunotherapy of IDO1 inhibitors in clinical trials." (PMID 33883013, 2021). "Increased expression of Kyn and IDO1, and reduced production of indoles have been detected in variety of cancers including CRC." (PMID 33916690, 2021). "From the pharmacological perspective, these overlapping events provide a reason for cancer cell resistance to IDO1 inhibition, as its role is taken over by the other two enzymes." (PMID 34071442, 2021). "Although IDO1 targeting in monotherapy has been shown to have disappointing efficacy in preclinical cancer models, their combinations with conventional treatments, immunogenic chemotherapy, or immunosuppressive drugs have shown satisfactory results." (PMID 34201791, 2021). "Despite the positive correlation between high IDO1 expression and advanced cancer stage or poor patient prognosis, the negative correlation is found in patients with RCC and contradictory correlations are documented in patients with HCC." (PMID 33557876, 2021). "The recently reported PROTAC degraders, limitations and challenges of IDO1 inhibitors for cancer immunotherapy are also discussed." (PMID 33883013, 2021). "Given the multifactorial role of the kynurenine pathway, it is not surprising that several treatments targeting this pathway have emerged from different medical fields, such as the currently implemented IDO1 inhibitors to treat cancer." (PMID 34770059, 2021). "Other than its role in modulation of the immune microenvironment, recent findings indicate that IDO1 promotes cancer cell development through effects on proliferation and metastasis." (PMID 34769098, 2021). "IDO1-dependent tryptophan metabolism in cancer has been investigated predominantly in the context of immune regulation and immunotherapy." (PMID 33831358, 2021). "To investigate the production of such metabolites from tryptophan in cancer cells expressing IDO1, we cultured cells with IFNγ in the presence of 13C11-tryptophan and performed liquid chromatography mass spectrometry (LC-MS) analysis." (PMID 33831358, 2021).
cancer (continued). "Addressing these limitations, we propose a method for direct IDO1 activity measurement in different human cancer cells based on the measurement of ʟ-Kyn production utilising a high-pressure liquid chromatography coupled with a diode array detector (HPLC-DAD)." (PMID 33541164, 2021). "The described data point to mutual permeating of immunological processes and cancer development, as well as indicate IDO1 as a significant factor that takes part in this mechanism." (PMID 34071442, 2021). "Nevertheless, in combination with the results for other types of cancer, the data obtained indicate that further work is promising to establish the parameters of the relationship between IDO1 expression and the prognosis of GC development." (PMID 34943606, 2021). "Accumulation of tryptophan metabolites results in immunosuppression through multiple mechanisms, and the overexpression of the predominant IDO isoform (IDO1) occurs in some cancers." (PMID 34299488, 2021). "IDO1 inhibitors are widely studied in various cancers as monotherapy or in combination with other therapies in preclinical and clinical trials." (PMID 35003126, 2021). "Indoleamine 2-dioxygenase-1 (IDO1), a tumor cell survival factor, can lead to the escape of many kinds of cancer cells." (PMID 34367714, 2021). "Yet, no studies to date have attempted to bring forward the idea of promoting or stabilising dormancy via regulating IDO1 as a potential strategy to control cancer progression." (PMID 34539663, 2021). "Further exploration of the link between attachment-independent growth and STAT3/IDO1 activation (e.g., in the context of metastasis formation) would help to better define the biological relevance of this phenotype to cancer." (PMID 33831358, 2021). "Apart from the cytotoxic properties that the investigated lichen-derived compounds and extracts exerted upon cancer cells, our study also revealed that they also possess desirable inhibitory effects on indoleamine-2,3-dioxygenase 1 (IDO1)." (PMID 34959693, 2021). "Given the significant clinical interest in IDO1, its known role as a metabolic enzyme, and the widespread engagement in cancer metabolism research, it is surprising that to date little effort has been made to interrogate the metabolic functions of this enzyme." (PMID 33831358, 2021). "We further validated these findings in pan-cancer analysis in TCGA database and found the correlation coefficients of PD-L1 and IDO1 in GC and CRC patients’ tissues were 0.701 (P < 0.001) and 0.783 (P < 0.001), respectively." (PMID 34175886, 2021). "Based on the role of IDO1 in cancer immunity and development, several small molecule drugs have been developed to inhibit IDO1 for many types of cancer including CRC." (PMID 33916690, 2021). "Many cancer types co-opt IDO1, TDO or both enzymes to accelerate tryptophan catabolism and escape immune destruction." (PMID 33708223, 2021). "The immunoregulatory enzyme indoleamine‐2,3‐dioxygenase (IDO1) strengthens cancer immune escape, and inhibition of IDO1 by means of new chemotypes and mechanisms of action is considered a promising opportunity for IDO1 inhibitor discovery." (PMID 33565680, 2021). "The paradigm would also provide a robust tool for fast assessment of the efficacy of IDO1-involved in regimens of precision cancer immunotherapies." (PMID 34148865, 2021). "The concentration of tryptophan was decreased significantly, whereas that of kynurenine was notably increased in IFN-γ-treated cancer cells, as well as in IDO1-overexpressing cells." (PMID 33390854, 2021). "The failure of phase III study of epacadostat posed the need for in-depth insights into the IDO1 pathway in cancers and the rational design of IDO1 inhibitors." (PMID 33883013, 2021). "Our methodology for IDO1 activity estimation can be an important clinical tool to study the impact of tryptophan metabolism in human cancer cells." (PMID 33541164, 2021).
cancer (continued). "Al‐Samadi et al34 showed that applying an IDO1 inhibitor in an in vitro 3D microfluidic chip assay with HSC‐3 induced immune cell migration towards cancer cells." (PMID 34053179, 2021). "Compared to IDO1, its upregulation is more frequently observed in autoimmune reactions but is also found in cancer." (PMID 34201791, 2021). "Recent studies have shown that IFN-γ upregulates immunosuppressive molecules such as PD-L1, PD-L2 and IDO1, in cancer and host cells, thereby increasing the response likelihood to ICIs therapy." (PMID 34993138, 2021). "Specifically, in cancer cells, IDO1 upregulation is mostly dependent on STAT1, and IL-27 regulation of PD-L1 occurs through signal transducer and activator of transcription 3 (STAT3)." (PMID 34944437, 2021). "IDO1 is widely expressed across different tissues and cells types (e.g., the colon, epididymis, dendritic cells, macrophages, reticular cells, and cancer cells)." (PMID 34203517, 2021). "In IDO1-expressing cancer cells, tryptophan is a bona fide one-carbon donor for purine nucleotide synthesis in vitro and in vivo." (PMID 33831358, 2021). "Kyn pathway, a tryptophan (Trp)-degrading enzymatic cascade controlled at the first rate-limiting step by indoleamine-2,3-dioxygenase 1 (IDO1), has been associated with a poorer prognosis in cancer patients." (PMID 33922388, 2021). "We analyzed correlations of different immune checkpoints in CCLE and TCGA database, and found the close correlation between PD-L1 and IDO1 in several types of cancers." (PMID 34175886, 2021). "Ongoing clinical trials report encouraging preliminary results, and the usefulness of IDO1 inhibitors as a strategy to enhance anti-PD-1 therapy activity in cancer is still under study." (PMID 34203535, 2021). "This means that IDO1, which is an immune checkpoint gene is an important target for cancer immunotherapy intervention." (PMID 34778035, 2021). "A series of human cancer cells constitutively express indoleamine 2,3-dioxygenase 1 (IDO1) that degrades tryptophan and produces equimolar amounts of kynurenine, also mediates immunosuppression." (PMID 33718229, 2021). "In a cancer model, Ido1−/− mice were shown to have a substantially lower pulmonary vascular density compared with Ido1-competent mice at baseline, predominantly at the level of small- and medium-sized vessels." (PMID 34770059, 2021). "We found that low-dose dexamethasone (0.1 mg/kg) not only inhibited the expression of PD-L1 and IDO1 of cancer cell simultaneously, but also reduced the expression of PD-L1 on CD4+ lymphocytes." (PMID 34175886, 2021). "Treatment of cancer cells in-vitro with IDO1-specific and/or TDO2 ASOs and small molecule inhibitors can reduce the production of KYN by cancer cells in a synergistic manner and increase proliferation of activated T cells in the co-culture." (PMID 34201791, 2021). "Although the IDO1 expression in most normal adult tissues is low, it is highly increased in a wide range of human cancers." (PMID 34539663, 2021). "The proposed HPLC-DAD method for estimation of IDO1 activity in human cancer cells was verified for accuracy using UHPLC-MS/MS as the reference method." (PMID 33541164, 2021). "Its implication in different pathophysiologic processes including cancer and neurodegenerative diseases has inspired the development of IDO1 inhibitors in the past decades." (PMID 33557876, 2021). "In the pancreas, IDO1 had a similar range of mRNA expression in healthy tissue compared to cancer cell lines grown in vitro." (PMID 33831358, 2021). "We believe that using the proposed here optimised and validated HPLC-DAD method for IDO1 activity assessment will turn into an important analytical tool in future work on IDO1 role in the pathology of human cancer and testing potential enzyme inhibitors." (PMID 33541164, 2021). "In this context indoleamine 2,3-dioxygenase 1 (IDO1) is one of the most studied target of cancer immunotherapies by virtue of its effects on immune suppression in the TME." (PMID 33557876, 2021).
cancer (continued). "The expression of the IDO1 enzyme is mainly upregulated in cancer cells; whereas, the levels of the KYNU enzyme are preferentially upregulated compared to IDO1 in inflammatory diseases." (PMID 34831399, 2021). "This approach revealed a cell-autonomous mechanism by which IDO1 tryptophan catabolites (kynurenine and quinolinic acid) directly promote cancer cell proliferation." (PMID 34306038, 2021). "The results confirm that herein proposed HPLC-DAD protocol for measurement of ʟ-Kyn produced by IDO1 in cancer cells provides accurate and reliable data." (PMID 33541164, 2021). "As inhibitors of IDO1, many flavonoids in Sophora flavescens have potential uses in cancer immunotherapy." (PMID 34367714, 2021). "Due to the mostly anti-inflammatory and cell-extrinsic effects of IDO1, its expression has been described as problematic in the setting of many cancers." (PMID 34149693, 2021). "The involvement of IDO1 activity in cancer immunoediting and growth seems to be so relevant that targeting this enzyme represents an attractive approach for cancer immunotherapeutic intervention." (PMID 33922388, 2021). "The upregulation of IDO1 has been detected in diverse human cancer types, and its prognostic significance in human cancers has been investigated in multiple studies." (PMID 34733885, 2021). "The human cancer cells with low basal IDO1 activity (MDA-MB-231) and thus low ʟ-Kyn production were selected for optimisation." (PMID 33541164, 2021). "So far, there are many small molecule compounds such as IDO1 inhibitors that have been reported to treat cancers alone or in combination with ICIs." (PMID 35003126, 2021). "Initially thought of as a “holy grail” for potentiating cancer immunotherapy, the disappointing outcomes of IDO1 inhibitors in clinical trials have generated scepticism." (PMID 33708223, 2021). "More importantly, the authors demonstrated that the BLPNs were actually effective for cancer immunotherapy, enhancing antitumor immunogenicity and IDO‐1 inhibition to improve the proliferation of CTLs." (PMID 33304763, 2020). "Indoleamine 2,3-dioxygenase 1 (IDO1) mediates tryptophan metabolism and T cell suppression, but the immune-independent function of IDO1 in cancer behavior is not fully understood." (PMID 32545442, 2020). "IDO1 is overexpressed in cancer cells, inhibiting the function of effector T cells and promoting the infiltration of Tregs." (PMID 33117084, 2020). "In contrast to its link to regulating immune responses in cancer, the effect of IDO1 on autoimmune responses has been less clear." (PMID 32973768, 2020). "Another approach to limit the immunosuppressive and cancer-promoting effects of IDO1-mediated and/or TDO2-mediated Kyn formation is depletion of extracellular Kyn by engineered KYNU." (PMID 31819194, 2020). "Indoleamine‐2,3‐dioxygenase 1 (IDO) is a key factor in defining cancer immunogenicity and is a cytosolic enzyme catalyzing the first and rate‐limiting step of tryptophan (Trp) catabolism." (PMID 32506804, 2020). "Metabolic strategies include enforced expression of PGC1α to reinvigorate dysfunctional T-cells for cancer treatment and targeting IDO1 production by cancer or myeloid cells." (PMID 32937961, 2020). "This manuscript reviews available data on IDO1 expression, mechanisms of its induction, and its function in cancer for each of these compartments." (PMID 33072086, 2020). "This demonstrates that the IFNγ-dependent Trp-catabolizing activity of the primary patient-derived cancer cells can be attributed to IDO1 activity, and can be selectively inhibited by NTRC 3883-0." (PMID 33584686, 2020). "Recent studies in IDO1-KO mice have highlighted a role for IDO1 in supporting neovascularization, particularly in inflammatory settings including oxygen-induced retinopathy and cancer." (PMID 33363543, 2020). "Inhibition of IDO1 was shown to increase the therapeutic efficacy of cancer vaccines, immune checkpoint inhibitors, or chemotherapy in multiple clinical mouse models." (PMID 32210078, 2020).
cancer (continued). "There exist only a small number of mouse cancer cell lines as compared to human cancer cell lines, and only a few have been reported to express IDO1 in vitro." (PMID 33584686, 2020). "The observation that IDO1 is elevated in several tumors spurred the development of inhibitors of IDO1 with the goal of inhibiting kynurenine production to allow the clearance of cancer cells by the patient's own T-cells." (PMID 31922097, 2020). "Aside from the IDO1 inhibitors themselves, the type of cancer in which IDO1 inhibition is studied is critical, as IDO1 inhibitors can only be effective if IDO1 is expressed and active." (PMID 31819194, 2020). "On the other hand, IFN-γ acts in a negative-feedback axis to elevate PD-L1 expression as well as other crucial immune inhibitory components, including IDO1, down-modulating the cytotoxic reaction and adaptive resistance to cancer cells." (PMID 33194652, 2020). "Over expression of IDO1 has been found in a variety of malignant tumors, such as ovarian cancer, pancreatic cancer, and non-small cell lung cancer." (PMID 33101032, 2020). "IDO1 is recognized as an important mediator of immunosuppression in cancer, and higher IDO1 expression has been found to play important role in immune escape and tumors resistant to immunotherapy." (PMID 33425745, 2020). "Due to its deregulated activity in human cancers, IDO1 is a possible target for combination therapies using IDO1 inhibitors (several in preclinical evaluation) and PD1/PD-L1 axis inhibitors." (PMID 32380691, 2020). "In cancer models, it was observed that IDO-1 and COX-2 activities are directly related, as PGE2 strongly inducesIDO1 transcription." (PMID 32051758, 2020). "Through induction of its first rate-limiting enzyme, indoleamine-2,3-dioxygenase 1 (IDO1), the KP has been associated with poorer prognosis in cancer patients." (PMID 33109232, 2020). "Another study in ovarian and adeno-squamous lung cancer cell lines demonstrated that cancer cells expressed IDO1 mRNA and constitutively released Kyn into the supernatant." (PMID 33072086, 2020). "The enzyme Indoleamine 2,3-dioxygenase 1 (IDO1) is overexpressed by cancer cells and DCs and metabolizes tryptophan into the metabolite kynurenine." (PMID 32090113, 2020). "Studies have found that the high content of IDO1 in various cancer tissues and their microenvironment is positively correlated with the degree of malignancy and metastasis of cancer." (PMID 33027968, 2020). "Many studies have shown that various malignant tumors highly express Indoleamine 2,3-dioxygenase-1 (IDO)." (PMID 32582152, 2020). "In our study, we characterized a MA signature consisting of three distinct genes (Cxcl11, Gbp1, Ido1), which correlates with the presence of M1 macrophages and mature DC in various cancer cohorts available in TCGA." (PMID 32486450, 2020). "The combination of IDO1 inhibitor and PD-1 antibody can significantly improve the efficiency of cancer immunotherapy." (PMID 33027968, 2020). "IDO1 expressed in myeloid cells and cancer cells is a rate-limiting enzyme that converts tryptophan to its immunosuppressive metabolite kynurenine." (PMID 33194652, 2020). "Among the IDO1 inhibitors, 1-methyl-D-tryptophan (MT, Indoximod) is a promising agent for anti-cancer therapy, therefore, there are clinical trials using MT." (PMID 32907554, 2020). "Different strategies have been applied for cancer patients regarding IDO pathway; such as inhibition of IDO1, AhR, Kyn, Trp-Kyn pathway and dual IDO1-TDO inhibition." (PMID 32499786, 2020). "Increased IDO1 expression and decreased tryptophan lead to dysfunctional effector T cells and cancer immune evasion." (PMID 32222150, 2020). "The results for other cancer types will be particularly interesting as well as results of combinations with other drugs for determining the therapeutic potential of IDO1 targeting." (PMID 33177494, 2020).